TRIP12 (thyroid hormone receptor interactor 12)
Diseases named in the same sentence as TRIP12 in open-access papers (continued):
Sharing a sentence is not in itself a finding about the gene and the disease.
language disorder (1 paper, 2025). A category of disorders characterized by an impairment in the development of an individual's language capabilities, which is in contrast to his/her non-verbal intellect. "The absence of facial features underscores the phenotypic variability of TRIP12 variants and supports the inclusion of TRIP12 in the genetic evaluation of ASD and language disorders." (PMID 41465129, 2025). "The report reinforces the relevance of TRIP12 analysis in the differential diagnosis of ASD and language disorders, even in individuals lacking physical traits, supporting more accurate genetic counseling and broader awareness of inherited TRIP12-related conditions." (PMID 41465129, 2025).
leukemia (1 paper, 2024). A malignant (clonal) hematologic disorder, involving hematopoietic stem cells and characterized by the presence of primitive or atypical myeloid or lymphoid cells in the bone marrow and the blood. "A study unveiled TRIP12's involvement in mediating the degradation of the tumor suppressor protein FBW7, influencing leukemia progression." (PMID 38706891, 2024).
lung carcinoma (1 paper, 2024). "The ability of TRIP12 to inhibit tumor growth in a lung cancer mouse model through CD8+ T cells 44 has also been documented." (PMID 38706891, 2024).
myeloma (1 paper, 2023). "Melphalan’s protein associations were highly distinct from those of bortezomib, with increased efficacy in myeloma cells with high expression levels of integrin B2 (ITGB2) and E3 ubiquitin-protein ligase TRIP12, among others." (PMID 37081258, 2023).
ovarian carcinoma (1 paper, 2023). A malignant neoplasm originating from the surface ovarian epithelium. "Finally, our data show that colorectal and ovarian cancer cells can be sensitized to Taxol by genetic inhibition of TRIP12 and this effect is largely dependent on FBW7 and MCL-1 proteins." (PMID 36672454, 2023). "Thus, to test whether TRIP12 inhibition will sensitize other cancer cells to Taxol, we knockdown TRIP12 in ovarian cancer cells and treated those cells with increasing doses of Taxol." (PMID 36672454, 2023). "Thus, our data suggest that TRIP12 targeting might sensitize FBW7 wild type ovarian cancer cells to Taxol therapy." (PMID 36672454, 2023). "Strikingly, TRIP12 depletion strongly sensitized FBW7 wild type ovarian cancer cells whereas FBW7R505L mutant cell line was resistant to Taxol treatment regardless of TRIP12 status." (PMID 36672454, 2023).
pancreatic adenocarcinoma (1 paper, 2020). "In contrast, an overexpression of TRIP12 mRNA is found in 15 types of cancer with a statistical significance for lymphoid neoplasm diffuse large B-cell lymphoma, thymoma and pancreatic adenocarcinoma." (PMID 33198194, 2020). "Of note, the TRIP12 mRNA level is decreased in tumor types for which TRIP12 mRNA is elevated in normal corresponding tissue, and inversely, it is up-regulated in tumors for which the TRIP12 mRNA level is low in corresponding normal tissues (i.e., pancreatic adenocarcinoma)." (PMID 33198194, 2020).
Parkinson disease (1 paper, 2025). A progressive degenerative disorder of the central nervous system characterized by loss of dopamine producing neurons in the substantia nigra and the presence of Lewy bodies in the substantia nigra and locus coeruleus. "Here, we show that the dynamic regulation of NRF2 stability and antioxidant signaling requires TRIP12, an essential E3 ligase that is dysregulated in Parkinson’s disease, a pathology that is characterized by aberrant ROS management." (PMID 40928944, 2025).
cancer (19 papers, 2013 to 2025). A tumor composed of atypical neoplastic, often pleomorphic cells that invade other tissues. "This was particularly evident for NSCLC patients, a subgroup of which also showed lower SUV39H1 protein levels in cancer samples with relatively higher TRIP12 that was associated with a favorable prognosis." (PMID 41125851, 2025). "Altogether, these studies suggest that although the TRIP12 gene is found mutated in various type of tumors at variable frequencies, the functional consequences of these mutations in cancer development remain largely unidentified." (PMID 33198194, 2020). "Among them, deletions in 4q (FAT1 and FBXW7) and 2q (TRIP12) affect genes that are frequently mutated in some cancer types, suggesting a tumour suppressor role of these ones." (PMID 29416628, 2018). "TRIP12 is an ubiquination-related gene less frequently reported as mutated in cancers." (PMID 29416628, 2018). "Thus, the TRIP12/FBW7/MCL-1 axis may provide a therapeutic target to overcome Taxol-associated chemotherapy resistance in cancer." (PMID 36672454, 2023). "In addition, TRIP12 mutations of unknown significance are reported in approximately 1–2% of human cancers." (PMID 37863914, 2023). "We show here a putative disparity in survival outcomes for cancer patients when stratified by expression of both TRIP12 and SUV39H1." (PMID 41125851, 2025). "According to The Cancer Genome Atlas (TCGA) Pan-Cancer analysis data on cBioPortal, approximately 4% of cancer patients exhibit TRIP12 alterations." (PMID 39048679, 2024). "In this context, TRIP12 has been found to reduce the sensitivity of cancer cells to PARP inhibitors (PARPi)." (PMID 39048679, 2024). "Next, to check if FBW7 stabilization alone would sensitize cancer cells and mimic TRIP12 deletion, we used lentivirus-mediated overexpression of wildtype and K404/412R FBW7 (2R) mutant in HCT116FBW7−/− cells which are otherwise resistant to Taxol." (PMID 36672454, 2023). "To check if TRIP12 can potentially regulate TGFβ mediated cancer cell migration, we generated CRISPR/Cas9 targeted crTRIP12 pools of MDA-MB-231 cells." (PMID 37863914, 2023). "In this study, we find that Taxol-induced mitotic block in cancer cells is partly controlled by TRIP12 via its positive regulation of MCL-1 protein." (PMID 36672454, 2023). "In this work we discover that another E3 ubiquitin ligase TRIP12 is required by cancer cells for efficient mitosis and completion of cell division." (PMID 36672454, 2023). "PARP1 accumulation mediated by TRIP12 dysfunction sensitizes BRCA-proficient cancer cells to PARP inhibitors through increased PARP1 trapping." (PMID 38201233, 2023). "TRIP12 plays an important role in Z363‐induced cancer cell apoptosis by directly and indirectly inhibiting MYC activity." (PMID 36639831, 2023). "In the cancer context, TRIP12 is a key regulatory player in oncogene-induced senescence (OIS), a major barrier against cancer initiation." (PMID 33963176, 2021). "As a preliminary step to study the role of TRIP12 in different cancers, online bioinformatics tools for meta-analysis were used to determine the clinical relevance of TRIP12 expression." (PMID 33963176, 2021). "Available data on TRIP12 protein expression in cancer are much less abundant than those describing TRIP12 mRNA levels." (PMID 33198194, 2020). "We also present the alterations of the TRIP12 gene found in neurodevelopmental disorders and cancers as well as the alterations of TRIP12 protein expression in cancers, and their consequences." (PMID 33198194, 2020). "The cBioPortal database (see Section Software and databases) provides the frequency of CNA (Copy Number Alteration) appearance in TRIP12 gene in cancers." (PMID 33198194, 2020). "Accumulating evidence indicate that TRIP12 ubiquitinates key proteins for cell homeostasis, regulates gene expression (See Section 5), and plays important roles in cancers and neurological diseases." (PMID 33198194, 2020).
cancer (continued). "RNF168 expression and signaling is deregulated in tumors and cancer cell lines by mechanisms that include increased mRNA expression, downregulation of TRIP12 and UBR5 proteases, as well as reduced expression of enzymes that de-ubiquitinate ub-H2AX." (PMID 32182354, 2020). "If we refer to the Gepia2 database (see Section Software and databases), the TRIP12 mRNA level compared to normal corresponding tissues varies depending on the type of cancer." (PMID 33198194, 2020). "Besides, Trp can enhance the toxicity of CD8+ T cells against cancer cells through the Trpylation of TRIP12, while down-regulating PD-1 expression and enhancing anti-cancer immune responses." (PMID 40696413, 2025). "TRIP12 is a member of the E3 ubiquitin ligases with involvement in important cellular processes and signaling pathways, including cell homeostasis, gene expression and cancer, with implications in cell cycle progression and maintenance of genome integrity." (PMID 37628571, 2023). "TRIP12 inactivation causes FBW7 protein accumulation and increased proteasomal degradation of the SCFFBW7 substrate Myeloid Leukemia 1 (MCL1), and sensitizes cancer cells to anti-tubulin chemotherapy." (PMID 33824312, 2021). "Although the role of TRIP12 as a potential promoter of cancer initiation has been studied, its role in various cancer types and in other cancer processes remains unknown." (PMID 33963176, 2021). "Indeed, among 27 different types of cancer, the down-regulation of TRIP12 mRNA is found in 12 cancer types compared to normal corresponding tissues but reached a statistical importance only in testicular germ cell tumors." (PMID 33198194, 2020). "Moreover, alterations of TRIP12 expression have been reported in cancers that can serve as predictive markers of therapeutic response." (PMID 33198194, 2020). "Only six publications have reported alterations in the TRIP12 gene in cancers." (PMID 33198194, 2020). "On average, the TRIP12 gene is altered in 1.84% of cancer patients (over 27,235 patients)." (PMID 33198194, 2020). "Thus, TRIP12/FBW7/MCL-1 axis is an important determinant of Taxol response in cancer cells." (PMID 36672454, 2023). "Therefore, the identification of TRIP12-deficient tumors and the development of TRIP12 inhibitors may allow the use of PARP inhibitors in the treatment of BRCA1 proficient cancers." (PMID 38201233, 2023). "Thus, TRIP12 regulates TGFβ signalling in normal as well as cancer cells." (PMID 37863914, 2023). "Thus, cancer cells may acquire chemotherapy resistance via different mechanisms and our findings suggest TRIP12 as a potential target to tackle MCL1-driven chemotherapy resistance." (PMID 33824312, 2021). "We next explored the relationship between TRIP12 and SUV39H1 protein levels in various cancer types." (PMID 41125851, 2025). "Here, we show that genetic deletion of TRIP12 led to FBW7-dependent downregulation of MCL1 protein and enhanced sensitivity to Taxol in cancer cells, phenotypes that were blocked by concomitant FBW7 mutation or deletion." (PMID 33824312, 2021). "Genetic deletion of TRIP12 stabilised FBW7 and enhanced FBW7-mediated degradation of its substrate MCL1, rendering cancer cells sensitive to the chemotherapy drug Taxol." (PMID 33824312, 2021). "The E3 ubiquitin-protein ligase TRIP12 (G5E870) is an integral part of ubiquitin fusion degradation pathway and is a protein of great interest in cancer because it regulates DNA repair pathways." (PMID 30481170, 2018). "TRIP12 depletion stabilizes FBW7 protein and sensitizes cancer cells in a FBW7-dependent manner." (PMID 36672454, 2023).
cancer (continued). "In this present study, we identified an inhibitory role for TRIP12 in suppressing epithelial-mesenchymal transition (EMT) and mesenchymal traits through regulating ZEB1/2 gene expression, contrary to its tumor-promoting role in cancer initiation." (PMID 33963176, 2021). "We observed the overexpression of isoforms of genes C3orf17, FRMD4A, FZD6, HNRNPA2B1, POSTN, PRKAA1, RRBP1 and VEGFA, and the under expression of TRIP12 isoform (ENST00000428959) in ACC patients who are not free of cancer, which is a surrogate for poor ACC outcomes." (PMID 33035235, 2020). "Additionally, TRIP12/MCL-1 expression might be a useful biomarker for texane-based chemotherapy response in some but not all cancers." (PMID 36672454, 2023).
tumor (14 papers, 2016 to 2025). "We observed Brd4, Cul3, and Trip12 to be commonly mutated genes across different tumor types, suggesting that there may be common mechanisms perturbed by the Onc2.3 transposon to drive tumorigenesis in the absence of oncogenic events." (PMID 33435458, 2021). "Animal experiments concurred, displaying that TRIP12 silencing mitigated HACE1's inhibitory impact on tumor growth and RAC1 protein levels in tumor tissue." (PMID 38706891, 2024). "For in vivo studies, we used Eca-109 cells in three groups: NC, HACE1, and HACE1+siTRIP12, and observed that TRIP12 silencing significantly exacerbated tumor growth on the basis of HACE1 overexpression." (PMID 38706891, 2024). "Through this process, it is proposed that TRIP12 plays an oncogenic role in tumor initiation and growth." (PMID 33963176, 2021). "Taken together, there is a consensus in the possible tumor-promoting role of TRIP12 through its proteolytic effect on p14ARF." (PMID 33963176, 2021). "However, the mechanisms responsible for the alteration of TRIP12 mRNA in tumor samples remain largely unknown." (PMID 33198194, 2020). "Apart from MAATS1, NCF1, and TRIP12, no other genes were mutated in more than one tumor." (PMID 27494029, 2016). "Most importantly, TRIP12 inhibition blocked HACE1-driven RAC1 ubiquitination and mitigated the inhibitory effects of HACE1 on ESCA cells, alleviating tumor growth in the tumor-bearing nude mouse model." (PMID 38706891, 2024). "Intriguingly, TRIP12 inhibition blocked HACE1-driven RAC1 ubiquitination and mitigated the inhibitory effects of HACE1 on ESCA cells, alleviating tumor growth in the tumor-bearing nude mouse model." (PMID 38706891, 2024). "Among the targets of TRIP12 is ASXL1, a tumor suppressor with roles in Polycomb-induced gene silencing." (PMID 33435458, 2021). "We suggested that other biallelic inactivation of FAT1, TRIP12 and CYLD (as well as PTEN) could occur through promoter methylation of these four genes in the tumours showing only monoallelic inactivation (only LOH without somatic mutation or only somatic mutation without LOH)." (PMID 29416628, 2018).
neurodevelopmental disorder (6 papers, 2020 to 2025). A behavioral and cognitive disorder with onset during the developmental period that involves impaired or aberrant development of intellectual, motor, or social functions. "This familial case of the TRIP12 p.Asp1135Val (rs778262518) missense variant expands the clinical spectrum of TRIP12-associated neurodevelopmental disorders." (PMID 41465129, 2025). "By studying these models, we can understand how altered USP7 and TRIP12 activity influences chromatin remodeling and DNA methylation, crucial for neurodevelopmental disorders and providing insights into disease mechanisms and potential therapeutic targets." (PMID 39135741, 2024). "TRIP12 (OMIM 604506 (Online Mendelian Inheritance in Man) (see Section Software and databases)) is a neurodevelopmental disorder (NDD)-associated gene." (PMID 33198194, 2020). "In addition, we performed analysis of differentially methylated regions as well as functional correlation of the TRIP12 genome-wide methylation profile with the profiles of 56 additional neurodevelopmental disorders." (PMID 36430143, 2022).
TRIP12 also shares sentences with these, for which no sentence is quoted: epilepsy (2 papers); brain malformations (1); cerebral malaria (1); gastric cancer (1); head and neck cancer (1); metabolic syndrome (1); Obesity (1); speech delay (1); testis cancer (1); virus infection (1).